FTO (FTO alpha-ketoglutarate dependent dioxygenase)
Diseases named in the same sentence as FTO in open-access papers (continued):
Sharing a sentence is not in itself a finding about the gene and the disease.
Obesity (continued). "Thus, this study aimed to examine the associations between FTO (rs9939609), FABP2 (rs1799883), LEP (rs2167270), LEPR (rs1137101), and MC4R (rs17782313) polymorphisms and obesity-related traits." (PMID 35627568, 2022). "As described in more recent research, FTO inactivation may prevent obesity, while over-expression of FTO induced the expression of ghrelin that controls intake behavior." (PMID 35628623, 2022). "FTO is well notorious for its role in obesity development and tumor occurrence." (PMID 36127345, 2022). "To date, the functional mechanisms explaining the interaction between risk of obesity, moderate wine consumption and genetic polymorphisms (including FTO rs9939609) have not been fully resolved due to the complexity of the factors involved." (PMID 36235854, 2022). "The FTO is a well-known gene involved in weight gain and obesity." (PMID 36376549, 2022). "Fat mass and obesity-related (FTO) mRNA was downregulated in osteonecrosis patients." (PMID 35706030, 2022). "According to a recent systematic review, the polymorphisms rs9939609 FTO and rs17782313 MC4R could be associated with overweight and obesity in children and adolescents." (PMID 36499740, 2022). "Interestingly, another FTO regulator pathway revealed that the promotion of FTO downregulated the obesity-related gene iroquois homeobox protein 3 (IRX3) level in the hypothalamus and macrophage." (PMID 36157445, 2022). "The FTO gene product is a protein (2-oxoglutarate-dependent nucleic acid demethylase) responsible for DNA repair and energy homeostasis control, which is mainly expressed in hypothalamus nuclei and therefore exerts an influence on fat mass and obesity." (PMID 34445769, 2021). "Other important m6A demethylase FTO KO mice are fertile but display an obesity phenotype." (PMID 34047466, 2021). "A GWAS study in Danish, Icelandic, Dutch, European Americans, and African American adults has shown that SNPs in the FTO, MC4R, BDNF, and SH2B1 genes are highly associated with obesity risk via modulating leptin secretion to induce leptin resistance in different ethnicities." (PMID 34836030, 2021). "Overall, this study argues that the FTO gene could play a significant role in developing obesity and the pathophysiology of obesity-related health complications, albeit more research, ideally of a prospective design, is needed to support these findings." (PMID 34912641, 2021). "Previous reports have shown the relationship between the A allele rs9939609 of the FTO gene and the increased risk of overweight and obesity in children, regardless of ethnicity, gender, or developmental stage." (PMID 34208143, 2021). "Interaction with obesity and central obesity was also observed between FTO rs8050136 and LTSB." (PMID 33668547, 2021). "Interestingly, several studies prior to the discovery of m6A indicated that FTO is closely related to obesity, telomere length, and other aging factors." (PMID 34315853, 2021). "Therefore, we focus on the relationship between obesity and the degree of methylation of FTO (FTO alpha-ketoglutarate dependent dioxygenase) and PLAG1 (pleomorphic adenoma gene 1 zinc finger) genes." (PMID 34063412, 2021). "It has been noted that the FTO effect on obesity and other comorbidities may be modulated by a healthy dietary pattern." (PMID 34829664, 2021). "The remaining studies used one to few selected SNPs in relevant obesity loci (e.g., FTO)." (PMID 34906131, 2021). "The roles of FTO gene and the level of serum 25-OH-vitamin D in obesity are frequently reported." (PMID 34399781, 2021). "Nevertheless, it is worth mentioning that SNPs of FTO gene may modify the effect of obesity on high blood pressure, at least in the Chinese child population." (PMID 34063412, 2021). "In addition, research consistent with this finding showed that the endothelial cell-specific knockdown of FTO protected against obesity-induced metabolic disorders and insulin resistance, and improved cardiac functions." (PMID 34881240, 2021).
Obesity (continued). "Therefore, the current study has been undertaken to compute the GRS based on five obesity-linked key loci including MC4R rs17782313, BDNF rs6265, FTO rs1421085, TMEM18 rs7561317, and NEGR1 rs2815752 in this at-risk and under-represented population." (PMID 33859285, 2021). "The observed association between an intronic variant in FTO and obesity is explained by the presence of an enhancer within this intron that interacts with the neighbouring IRX3 gene and alters its expression with an impact on obesity." (PMID 34461824, 2021). "FTO overexpression increases food intake and promotes obesity." (PMID 34150765, 2021). "Our GWAS analysis in UKB also pointed to FTO, a well-established obesity locus." (PMID 34903748, 2021). "Nevertheless, there are reports of associations of FTO polymorphism with the susceptibility of developing various cancer independent of obesity." (PMID 34650918, 2021). "A recent study showed that deletion of fat mass and obesity-associated protein (FTO) in EC rescued metabolic and vascular function in obesity, independent of its known function in regulation of obesity." (PMID 34277732, 2021). "Further, a population cohort study found that the role of FTO risk genes is related to energy intake; however, the mechanisms by which FTO influences obesity and the specific pathways related to energy metabolism remain unclear." (PMID 34368154, 2021). "Besides FTO polymorphisms, KCNJ11 rs5219, KCNQ1 rs2237892, and TCF7L2 rs7901695 variations have previously been linked to obesity in patients with T2DM." (PMID 34442333, 2021). "Results of relative genetic expressions in subjects with overweight/obesity showed significant downregulation in the FTO gene expression at the end of Ramadan in comparison with the pre-fasting level, with a percent reduction of about−32% (95% CI–0.052 −0.981)." (PMID 35372458, 2021). "Overactivation of FTO can increase food intake, which leads to obesity." (PMID 34630412, 2021). "Monogenic obesity results from highly infrequent single genes mutations (such as LEP, POMC); however, some of them also demonstrated an association with polygenic obesity (e.g., MC4R, FTO)." (PMID 34445769, 2021). "A significant interaction was found between dietary energy intake and FTO rs8050136 (p = 0.004), in which participants with a higher dietary energy intake had a more obvious effect of FTO rs8050136 on obesity compared to those with a lower dietary energy intake (OR = 1.77, 95%CI:1.20–2.62)." (PMID 33668547, 2021). "We found that FTO, as an adiposity and obesity-related gene and an adipose metabolism-related gene, was the most promising LHD-binding candidate and may play a regulatory role in PA-induced inflammation process." (PMID 34881240, 2021). "Similar difficulty was observed in the FTO locus of individuals with obesity." (PMID 32948841, 2021). "Telomere length attrition may be affected by obesity-related inflammation, oxidative stress, and FTO gene pathways." (PMID 34150765, 2021). "However, we are unaware of any possible role of FTO associated with hair growth, although a previous study showed the possible role of POMC in severe early‐onset obesity in humans." (PMID 33410284, 2021). "The genetic variations in the FTO gene are associated with pancreatic cancer risk through a possible mechanism that is independent of obesity." (PMID 34458141, 2021). "Several SNPs of the human FTO gene (fat mass and obesity-associated, NM_001080432) have been associated with body mass index (BMI) and susceptibility to type 2 diabetes mellitus (T2DM) and obesity." (PMID 33729310, 2021). "Moreover, it’s reported that FTO genotype effects on obesity are more pronounced among people with insufficient 25-OH-vitamin D levels." (PMID 34399781, 2021). "Fat mass and obesity can catalyse and mediate the demethylation of m6A, therefore, downregulated FTO in the villi of SA patients may lead to the disorder of m6A modification." (PMID 34350169, 2021).
Obesity (continued). "The FTO gene has a well-described relationship with obesity." (PMID 34063412, 2021). "Current data from the literature indicated that FTO expression could be elevated in children with obesity and our results confirmed this hypothesis." (PMID 34063412, 2021). "Originally, FTO was thought to be a protein that regulates body weight and obesity." (PMID 34630412, 2021). "Later data suggested that the mentioned SNPs in question did not in fact affect the FTO gene but instead changed the regulatory sequence of another obesity-associated gene located on chromosome 16, IRX3." (PMID 33925955, 2021). "Even though it is not fully clear how FTO variants influence obesity, FTO associations with several EDs, including BED, are apparent." (PMID 34959873, 2021). "The inactive/high intake women had a 39.0% greater risk of obesity associated with each A allele in FTO carried when compared with the non-carriers." (PMID 33668547, 2021). "Higher adherence to the Mediterranean dietary pattern using Mediterranean diet scores was associated with a decrease in obesity, regardless of FTO risk alleles." (PMID 34095191, 2021). "Moreover, highly significant differences were identified for the eraser FTO (P=2.257x10-4), the strongest obesity candidate gene identified in genetic studies." (PMID 34950106, 2021). "The study also revealed a 3.35% hypomethylation at a CpG site, located within the intron 1 and 11 bp upstream of the obesity and T2D-associated rs1121980 of the FTO gene, in T2 diabetics (n = 198) relative to non-diabetics (n = 233)." (PMID 34769081, 2021). "Furthermore, fat mass and obesity-associated (FTO)-mediated N6-methyladenosine demethylation downregulated AC008 transcription, while lower FTO expression led to upregulation of AC008 transcription in OA." (PMID 34737423, 2021). "Moreover, lifestyle modification appeared to have an impact on obesity through changes in the expression of the FTO and IRX3 genes." (PMID 34038448, 2021). "We conclude that in subjects with similar obesity we did not register any FTO risk-allele effect on hepatic IS." (PMID 33684170, 2021). "In conclusion, our results indicate that daily macronutrient intake may modulate the impact of FTO genetic SNPs on obesity and obesity-related metabolic consequences." (PMID 33114268, 2020). "Common genetic variants in FTO have been associated with an increased risk of T2DM and obesity." (PMID 32653024, 2020). "FTO gene is located in chromosome 16q12.2, reported to be consistently related to obesity and BMI." (PMID 32390949, 2020). "Based on these findings, the correlation between FTO SNPs and obesity and cancer may be due to the regulation of FTO enzyme activity or expression of adjacent genes." (PMID 33304380, 2020). "FTO (rs3751812) can promote obesity by altering fat deposition and disturbing serum lipid profile." (PMID 32110378, 2020). "The FTO locus was identified among the most relevant loci, which is in accordance with previous studies pointing out the FTO as a central piece within the genetics architecture of obesity." (PMID 32498346, 2020). "Summary of the effects and application of FTO inhibitors in obesity and cancer." (PMID 33304380, 2020). "FTO, serving as an m6A demethylase, primarily controls the m6A levels of downstream targets by their 3' untranslated regions and plays an important role in obesity‐related diseases and the occurrence, development and prognosis of multiple types of tumours." (PMID 32961012, 2020). "FTO has beenrecognized as an important genetic factor for obesity development." (PMID 32154826, 2020). "For example, overexpression of the demethylase FTO results in increased food intake and obesity." (PMID 32411802, 2020). "Disruption of circadian rhythms and variations in the FTO gene may interfere with energy homeostasis and play a role in the development of obesity." (PMID 32785234, 2020).
Obesity (continued). "This last GWAS identifies strong associations with extreme obesity, including established variants in the FTO and NEGR1 genes, as well as loci not yet linked to obesity." (PMID 31888951, 2020). "FTO inhibitors have also been found to share anti-obesity and anti-cancer effects in vivo." (PMID 33304380, 2020). "The belief that FTO could affect human obesity led to intense interest in understanding its function." (PMID 32299393, 2020). "Science entacapone is already an FDA-approved drug, and it could be readily generalizable to other clinical indications that are related to FTO, such as cancer and obesity." (PMID 33072775, 2020). "Applying RIDGE to 18,424 subjects in the Taiwan Biobank, we showed that performing regular exercise can attenuate the adverse influence of the FTO gene on four obesity measures: BMI (p = 0.0009), body fat percentage (p = 0.0031), waist circumference (p = 0.0052), and hip circumference (p = 0.0001)." (PMID 32457790, 2020). "FTO is one of the best examples of a diabetogenic gene that promotes its impact through obesity." (PMID 33113859, 2020). "Similarly, the link between the FTO gene and obesity was first reported in mice prior to the identification of this gene's association with obesity in humans." (PMID 33643372, 2020). "Inthe last decades, individuals have changed the lifestyle, resulting in energyimbalance caused by excessive food intake and diminished physical activity.Regarding genetic factors, the FTO gene has been recognized as oneof the main contributors to polygenic obesity." (PMID 32154826, 2020). "Polymorphisms in the intron regions of FTO gene may act as a regulator of other genes such as Iroquois homeobox 3 (IRX3) and obesity-associated single nucleotide polymorphisms of FTO were associated with expression of IRX3, but not FTO, in human brains." (PMID 32843047, 2020). "Because of the established functions of FTO in obesity and diabetes, it has been proposed that FTO may also play a role in NAFLD development." (PMID 32111216, 2020). "Since FTO has been identified as the first obesity-related gene." (PMID 33304380, 2020). "FTO regulates the amount of fat deposition and affects T2D risk through its effect on BMI; indeed, people homozygous for a particular FTO allele weighed about 3 kg more and had a 1.6-fold greater rate of obesity than those who had not inherited this trait." (PMID 33142938, 2020). "While most studies examining the effect of the FTO obesity SNPs on blood lipids have assessed fasting concentrations, higher postprandial TG concentrations are crucial in the development of atherosclerotic plaques via oxidative stress and display stronger relationships with CVD than fasting levels." (PMID 33348678, 2020). "FTO has been widely studied since its relationship with obesity was discovered." (PMID 32733807, 2020). "Unlike PPARγ rs1801282, FTO rs9939609 is an intronic variant that was first identified via GWAS to be associated with obesity, conferring risk for T2DM." (PMID 31947684, 2020). "Recent studies show that obesity-linked FTO mutations do not affect the FTO protein though they are the most common genetic contributor to obesity." (PMID 32299393, 2020). "Overall, previous literature provides strong support for a potential role of FOXA1 in CRC which may be mediated through the FTO gene that could explain the observed interaction with obesity." (PMID 32207560, 2020). "BATLAS genes assembled very similarly, 75% of the FTO T/T and 83% of the FTO C/C donor samples clustered in the same main groups and FTO obesity-risk samples appeared closer to the non-thermogenic preadipocytes." (PMID 32316277, 2020). "The FTO gene encodes a dependent oxygenase related to 2-oxoglutarate that has a role in DNA demethylation but its molecular mechanism in obesity and metabolism has not been elucidated." (PMID 31555578, 2019).
Obesity (continued). "In addition, it was reported that the FTO gene realizes its effect on body composition and obesity in interaction with other genes, such as FTM (RPGRIP1L) and Irx3, which are localized near it." (PMID 31810473, 2019). "In a study on the Turkish population, the relationship between obesity, metabolic syndrome, and insulin-related parameters of the FTO gene’s rs9939609 and rs1421085 SNPs were investigated in 1967 individuals in the Turkish Adult Heart Disease and Risk Factors (TEKHARF) cohort." (PMID 31810473, 2019). "Individuals who are homozygous for FTO risk alleles are on average at 1.67-fold increased odds of obesity and 3 kg heavier in comparison to individuals without any risk alleles." (PMID 31516636, 2019). "Variations in the FTO gene can not only regulate D2R-dependent reward learning, but also affect nerve adjust food visual, produce more frequent rewards, affect the control of mood and impulse, and affect obesity by regulating brain signaling pathways." (PMID 31452869, 2019). "Associations between FTO variants with obesity risk (measured by BMI) have not been widely investigated in Taiwan." (PMID 31075924, 2019). "In 2007, the well-known obesity gene, FTO, was first identified in a European ancestry population." (PMID 31852448, 2019). "Thus, our results suggest that A carriers interfere with FTO activity in subjects with obesity, increasing the HbA1c levels in T2D subjects." (PMID 30764545, 2019). "The hypothesis may be raised that a potential effect of genotype on tissue FTO gene expression levels may be unmasked in obesity." (PMID 31126299, 2019). "The FTO rs3751812 obesity risk T allele is also negatively associated with lack of premeditation and lack of perseverance in our study." (PMID 31772290, 2019). "Therefore, the different levels of FTO expression in populations with different BMIs are considered as other obesity-related mechanisms." (PMID 31810473, 2019). "Especially the single nucleotide polymorphism (SNP) (rs9939609) and mutations in the first intron of the FTO gene (in the non-protein coding area) have been reported to be associated with obesity in children and adult populations." (PMID 31810473, 2019). "Molecular docking analysis of twenty two phytoconstituents from Hibiscus rosa-sinensis, against seven targets of obesity like pancreatic lipase, fat and obesity protein (FTO protein), cannabinoid receptor, hormones as ghrelin, leptin and protein as SCH1 and MCH1 is detailed in this data article." (PMID 31193691, 2019). "Approximately 16% of subjects homozygous for the risk allele of FTO weighed at minimum 3 kg more than subjects lacking the allele, with a 31% increased risk of developing obesity as compared to those subjects containing the non-risk allele." (PMID 31482095, 2019). "However, it was determined that rs1421085 SNP showed linkage disequilibrium and FTO gene rs1421085 SNPs contributed to obesity independently in females and BMI-related metabolic syndrome and insulin resistance in males among Turkish adults." (PMID 31810473, 2019). "Overall, these studies report that adherence to a Mediterranean Diet and/or calorie restriction were associated with decreased DNA methylation in obesity-related genes such as PDK4, KCNQ1, WT1, SH2B1, FTO, BDNF, and PPARGC1A or inflammatory genes such as TNF-α." (PMID 31506096, 2019). "On the other hand, they did not observe any significant relationship between FTO polymorphism and obesity." (PMID 31200723, 2019). "Genetic variants in FTO gene are highly relevant in obesity and to assess whether LGI-Ob score would perform better than FTO on its own, we tested the removal of FTO polymorphism from the model." (PMID 30704070, 2019). "The CXCL12 rs501120 C allele and the FTO rs9939609 A allele were risk factors (rs501120: OR = 1.96, p = 0.02; rs9939609: OR = 2.2, p = 0.04), while LEP rs7799039 was a protective factor (rs7799039: OR = 0.6, p = 0.03) in the obesity group." (PMID 30764545, 2019).